GSDMC (gasdermin C)
Diseases named in the same sentence as GSDMC in open-access papers (continued):
Sharing a sentence is not in itself a finding about the gene and the disease.
tumor (continued). "In addition, caspase 8 cleaves GSDMC to create GSDMC‐NT, which triggers tumor necrosis by forcing cancer cells to undergo pyroptosis instead of apoptosis." (PMID 37752941, 2023). "However, recent studies have suggested that GSDMC in cancer cells is capable of switching apoptosis to pyroptosis, thereby leading to tumor necrosis." (PMID 37741915, 2023). "In addition, caspase-8 in tumor cells can be activated by TNF-α to cleave GSDMC, while in murine macrophage, activation of caspase-8 in the context of TAK1 inhibition results in cleavage of both GSDMD and GSDME." (PMID 36823153, 2023). "Interestingly, GSDMA and GSDMC presented relatively higher gene expression levels in all tumor types compared with matched normal tissues." (PMID 36003332, 2022). "Generated GSDMC N-terminal domain induced tumor necrosis by switch apoptosis to pyroptosis." (PMID 35957895, 2022). "At the same time, the heatmap showed that AIM2, GSDMB and GSDMC were overexpressed in tumor group." (PMID 36034461, 2022). "In addition, the knockout of TGFBR2 in CRC resulted in the upregulation of the GSDMC expression and promoted the proliferation of tumor cells." (PMID 36142404, 2022). "In summary, GSDMC-mediated CCP promotes tumor necrosis and restrains tumor development." (PMID 36142404, 2022). "Therefore, for another crucial facet of this study, we explored the link between GSDMC and tumor immune infiltration in BRCA." (PMID 36042287, 2022). "GSDMB and GSDMC are considered to be tumor suppressor genes in GC." (PMID 36142404, 2022). "Following caspase-8 activation in tumor cells, GSDMC has been found to mediate tumor necrosis." (PMID 35992142, 2022). "Select chemotherapeutic agents have also been described to activate caspase-8-dependent GSDMC activation in tumor cells, or GSDMD activation in myeloid cells, however, whether myeloid GSDMD activation promotes or dampens tumor growth in vivo remains unclear." (PMID 33868312, 2021). "These elevated levels of GSDMC increase the tumor cell proliferation, recommending that GSDMC may be a hopeful therapeutic target." (PMID 34571825, 2021). "It is suggested that GSDMC has the potential to serve as a tumor suppressor." (PMID 34459122, 2021). "Collectively, this study not only identifies the key node protein (DR6), pyroptosis initiator (caspase-8), and executor (GSDMC) in the α-KG-induced pyroptotic pathway but also provides an important research direction for clinical tumor treatment via pyroptosis induction." (PMID 34012073, 2021). "This study not only illustrates a pyroptotic pathway linked with metabolites but also identifies an unreported principal axis extending from ROS-initiated DR6 endocytosis to caspase-8-mediated cleavage of GSDMC for potential clinical application in tumor therapy." (PMID 34012073, 2021). "Interestingly, the current study revealed that TNF α - activated caspase-8 switched apoptosis to pyroptosis in the presence of hypoxia-activated GSDMC and nPD-L1, leading to tumor necrosis in hypoxic regions." (PMID 35047554, 2021). "The function of GSDMC in tumor progression is controversial." (PMID 34012073, 2021). "There were still few studies on GSDMC in tumor treatment, and further research was still needed." (PMID 34778452, 2021). "GSDMC may serve as a significant therapeutic target in CRC patients as it promotes tumor cell proliferation in CRC by reducing activation of the transforming growth factor β receptor type II." (PMID 34459122, 2021). "However, co-injection of lactic acid with DM-αKG significantly decreased tumor sizes and weights, accompanied by GSDMC cleavage." (PMID 34012073, 2021). "However, GSDMC expression is suppressed in some cell lines of both esophageal and gastric cancers, supporting its potential role as an anti-tumor agent." (PMID 34298833, 2021).
tumor (continued). "Moreover, tumor weights were significantly reduced in mice inoculated with GSDMC-knockdown cells compared with that in mice inoculated with control cells (116.6 ± 114.1 versus 315.8 ± 268.8 mg, respectively; p < 0.05)." (PMID 27835699, 2016). "In addition, in many tumor types, patients with high GSDMC expression have a poor prognosis." (PMID 41584044, 2026). "However, the other animal study showed that long-term chronic cell death might promote tumor growth and GSDMC expression was correlated with PD-1 expression and poor clinical outcomes in triple-negative breast cancer patients." (PMID 40064873, 2025). "In addition, GSDMC exhibits cell growth inhibition activity, which indicates it may act as a potential tumor suppressor." (PMID 39062587, 2024). "Importantly, GSDMC promoted tumor clearance independent of BRCA deficiency in multiple cancer types with PARPi treatment." (PMID 37883181, 2024). "Thus, assessment of GSDMC expression level in tumor tissues may help optimize clinical trials of these DDR inhibitors." (PMID 37883181, 2024). "Next, we asked whether GSDMC-mediated CCP might affect tumor response to PARPi." (PMID 37883181, 2024). "A recent study found that PD-L1 can promote tumor progression by upregulating the expression of GSDMC, which is involved in pyroptosis, suggesting that pyroptosis may be related to tumor immune escape and providing new ideas for cancer prevention and treatment." (PMID 37214439, 2023). "Moreover, studies have revealed that α-KG can induce pyroptosis to inhibit tumor growth by activating caspase-8 and cleaving gasdermin C, suggesting that caspase-8-mediated pyroptosis may enhance the efficacy of antitumor drugs." (PMID 37214439, 2023). "In addition, accumulated α-KG blocks tumor growth by inducing gasdermin C (GSDMC)-mediated pyroptosis, indicating that cell death induction by α-KG may be considered a potential strategy for cancer." (PMID 37308557, 2023). "Moreover, the expressions of CASP6, GPX4, GSDMC, and NOD2 could increase the susceptibility of tumor cells to paclitaxel, 5-fluorouracil, dasatinib, and gefitinib." (PMID 35368686, 2022). "Finally, the pro‐tumor phenotype of GSDMC was explored in PANC-1 and CFPAC-1 cells." (PMID 36199146, 2022). "Furthermore, GSDMC shRNA resulted in a significant decrease in xenograft tumor growth in mice." (PMID 34858408, 2021). "Furthermore, GSDMC promoted tumor cell proliferation in colorectal carcinogenesis and may be a promising therapeutic target for patients with CRC having TGFBR2 mutations." (PMID 27835699, 2016). "Moreover, GSDMC was upregulated by TGFBR2 mutation in CRC and promoted tumor cell proliferation in CRC carcinogenesis, suggesting that GSDMC may be a promising therapeutic target." (PMID 27835699, 2016). "The intraperitoneal injection of DdBIC significantly suppressed tumor growth (top), with related events, including GSDMC and OPA1 cleavage, eIF2α phosphorylation, and a decrease in heme levels, detected in the same tumor samples (bottom)." (PMID 41407678, 2025). "Another study reported that upregulation of GSDMC in HCC contributes to cell proliferation and tumor progression." (PMID 41291696, 2025). "In hypoxic tumor microenvironments (TME), macrophage-derived TNF-α promotes cancer cell pyroptosis via caspase-8-mediated cleavage of GSDMC." (PMID 40200299, 2025). "In vivo, okanin reduced tumor growth and involved pyroptosis-related markers such as CASP1, GSDMC, GSDMD, and GSDME." (PMID 39335166, 2024). "Here, GSDMC expression was correlated to a reduction in tumour growth and volume, suggesting α-KG treatment shifts the GSDM from a pro-tumoral role to an anti-tumour pyroptotic function." (PMID 37266429, 2023). "In other investigations, GSDMA, GSDMB, GSDMC, and GSDMD have also been shown to have tumor-suppressing properties." (PMID 35769504, 2022). "In addition, activated caspase 8 could cleave Gasdermin C (GSDMC) to trigger tumor pyroptosis." (PMID 36280674, 2022).
tumor (continued). "Three genes (ELANE, NLRP7, and CASP5) were downregulated, whereas seven others (GSDMC, IL1A, NOD2, GZMB, GSDMA, IL1B, and PLCG1) were overrepresented in the tumour group." (PMID 35087586, 2022). "Based on the analysis of UALCAN, the expression of all GSDM family members was increased in tumor-stage 1–3 subgroups, and the expression of GSDMA, GSDMB, GSDMC, and PJVK was higher in all four tumor-stage subgroups than in normal subgroups." (PMID 36505798, 2022). "Immunohistochemistry (IHC) was used to evaluate the differential expression of major PRGs (GSDMC, GSDMD, GSDME, NLRP3, NLRC4, IL1B) in selected tumor types (COAD, HNSC, KIRC, LIHC, LUAD, LUSC)." (PMID 36605187, 2022). "Gene expression also differed in the same tumor, with IL6 and NLRP6 being low expressed in kidney chromophobe (KICH) while GSDMC was high." (PMID 35795676, 2022). "In conclusion, α-KG functions as an antioncogenic metabolite to inhibit tumor growth and metastasis via a DR6- and GSDMC-mediated pyroptotic pathway." (PMID 34012073, 2021). "For several cancer subtypes, pyroptosis promotes tumor growth and metastasis through inflammatory cytokine release, activation of oncogenic signaling pathways (e.g., STAT3, PI3K), and dysregulation of gasdermin proteins (e.g., GSDMB, GSDMC)." (PMID 40200299, 2025). "Thus, during the PARPi treatment GSDMC-mediated CCP augments antitumor immunity by promoting the activation and tumor infiltration of cytotoxic and memory T cells." (PMID 37883181, 2024). "We further sought to confirm whether PA-induced cleavage of GSDME, including other gasdermin family proteins GSDMC and GSDMD, which have received much attention in tumor research." (PMID 39138191, 2024). "While tumor formation was comparable for both groups, we still found abundant liver metastases in GSDMC overexpressing tumors (DOX) compared to no detectable metastases for the control group." (PMID 39297408, 2024). "In tumor cells, TNF-α triggers caspase-8, leading to GSDMC cleavage at the D365 amino acid." (PMID 38304430, 2024). "GSDMC and PJVK expression levels in tumor grade 1 and 3 differed from normal tissues, respectively." (PMID 39607202, 2024). "GSDMC-mediated CCP increased memory CD8+ T cell population in lymph node (LN), spleen, and tumor and, thus, promoted cytotoxic CD8+ T cell infiltration in the tumor microenvironment." (PMID 37883181, 2024). "mRNA expression levels of GSDMC and GSDME were correlated to tumor purity." (PMID 39607202, 2024). "In some cases, enhanced expression of GSDMC promotes tumour aggression and growth, suggesting the pyroptotic function of GSDMC is not a critical determinant of its ability to influence tumour homeostasis." (PMID 37266429, 2023). "In addition, PD-L1-mediated gasdermin C (GSDMC) expression transforms apoptosis to pyroptosis and facilitates tumor necrosis in cancer cells." (PMID 37061535, 2023). "However, GSDMC was found in one work to be suppressed within multiple ESCC cell lines, indicating its role as a tumor suppressor." (PMID 36552744, 2022). "In LIHC, correlation analysis of gasdermin family gene expression with tumor microenvironment revealed that GSDMA and GSDMC expressions were positively related to stromal score, whereas GSDMB and PJVK expressions were negatively associated with the stromal score." (PMID 35922531, 2022). "In DR6 knockdown HeLa cells, re-expression of DR6WT restored the suppressive effects of α-KG on xenograft tumor growth and GSDMC cleavage; however, transfection of DR65CS failed to do so." (PMID 34012073, 2021). "However, it has been reported that GSDMA, GSDMC, and GSDMD have the effect of inhibiting tumor proliferation." (PMID 34778452, 2021). "Clearly, α-KG inhibited tumor growth by inducing pyroptosis in a DR6- and GSDMC-dependent manner." (PMID 34012073, 2021). "However, the results revealed that BRQ treatment did not activate GSDMA, GSDMB, or GSDMC in tumor cells." (PMID 41144149, 2025).
tumor (continued). "According to the identified mechanisms in the study, the sensitization effect of GSDMC in tumor suppression may not be limited to PARPi." (PMID 37883181, 2024). "Thus, our studies in this model do not support an important role for GSDMC in proliferation or cell death in vivo or in other mechanisms that alter tumor growth." (PMID 39489845, 2024). "Furthermore, GSDMC is specifically cleaved by caspase‐8 after treatment with TNF‐α or chemotherapy drugs, such as doxorubicin (DOX), epirubicin, and actinomycin D, thereby switching apoptosis to pyroptosis and facilitates tumor necrosis." (PMID 37125240, 2023). "Interestingly, PRGs with CNV gain, including GSDMD, GSDMC, CHMP4C and CHMP6, were significantly higher in HCC samples than in adjacent non-tumor samples (p < 0.001), suggesting that CNVs may regulate PRGs expression." (PMID 36650832, 2023). "However, the protein expressions of GSDMC were hardly detected no matter in normal and tumor samples." (PMID 35000541, 2022). "Moreover, nuclear PD-L1 is able to modulate the non-canonical pyroptosis pathway mediated by GSDMC/CASP8 to induce tumor necrosis in cancer cells in hypoxic conditions." (PMID 35725836, 2022). "However, there is no consensus on the function of GSDMC in cancer, as it exerts pro- and anti-tumor activity in different tumor types." (PMID 34858408, 2021). "Due to promoter or mRNA methylation, GSDMA, GSDMC, and GSDME are expressed at low levels or are not in tumours." (PMID 35289335, 2022). "Not surprisingly, the high expressions of GSDMA, GSDMC, GSDMD and GSDME were observed correlated with low tumor purity." (PMID 35164740, 2022). "In the study, gain of MYC or the PVT1/CCDC26/GSDMC region alone did not result in tumourigenesis, but co-amplification of MYC and PVT1/CCDC26/GSDMC resulted in a pro-tumour transformation." (PMID 33499210, 2021). "GSDMA, GSDMC and PJVK are not detected in most human tissues (both tumor tissues and normal tissues), while GSDMB, GSDMD and GSDME are highly expressed in most human tissues (both tumor tissues and normal tissues), especially GSDMD." (PMID 34421915, 2021).
cancer (81 papers, 2016 to 2026). A tumor composed of atypical neoplastic, often pleomorphic cells that invade other tissues. "Gasdermin C genes are upregulated by type 2 immunity, yet appear dispensable for the development of intestinal inflammation, infection and colitis-associated cancer." (PMID 39489845, 2024). "This study emphasizes the potential value of GSDMC as a general biomarker that expands the population of patients with multiple cancer types likely to benefit from PARPi beyond BRCA mutation carriers." (PMID 37883181, 2024). "Nevertheless, PARPi works better in BRCA-deficient tumors than in BRCA-proficient tumors, indicating that BRCA mutation is still a good marker for PARPi treatment even in GSDMC-positive cancer types." (PMID 37883181, 2024). "Elevated GSDMC expression has been associated with poor prognosis in various cancers, including lung adenocarcinoma, breast cancer, gastric cancer, colorectal cancer, and clear cell renal cell carcinoma." (PMID 38066523, 2023). "PRGs with consistent enhanced expression and association with poor survival in cancers included GSDMC in BRCA, KIRC, LIHC, PAAD, UVM and KICH; DFNA5 (GSDME) in COAD, STAD, UCEC, HNSC, KIRC; and AIM2 in KIRP, KIRC, UVM, and PAAD." (PMID 36605187, 2022). "Pyroptosis is implicated in tumorigenesis, but the role of GSDMC in cancer cells is yet to be fully elucidated." (PMID 36042287, 2022). "Dysregulated GSDMC is associated with a variety of cancers and its functions are tissue-specific." (PMID 36523974, 2022). "Consequently, upon TNF-induced caspase-8 activation, caspase-8 cleaved GSDMC at 362 LELD 365 to release a pore-forming N-terminal domain causing cancer cell pyroptosis." (PMID 35608339, 2022). "A study also showed that α‐KG induces pyroptosis through caspase‐8‐mediated cleavage of Gasdermin C (GSDMC) in some types of cancer cells, including HCT116." (PMID 40259435, 2025). "GSDMC, while highly expressed in pancreatic ductal adenocarcinoma (PDAC), is linked to cancer stemness and metastasis." (PMID 40691738, 2025). "Agents like PD-L1, TNF-α sourced from macrophages, certain medications, and cancer treatments can induce breast cancer cell pyroptosis via the caspase-8/GSDMC route." (PMID 38304430, 2024). "Taken together, these data suggest that GSDMC increases PARPi sensitivity in both BRCA-proficient and -deficient tumors with much more potency in the BRCA-deficient cancer cells." (PMID 37883181, 2024). "PARPi can promote caspase-8/GSDMC-mediated pyroptosis, while GSDMC can promote cancer cell sensitivity to chemotherapy drugs via activating caspase-6/8." (PMID 39273650, 2024). "Meanwhile, high levels of GSDMC can increase the sensitivity of cancer cells to poly (ADP-ribose) polymerase inhibitors (PARPi)." (PMID 39273650, 2024). "In metastatic melanoma and colorectal cancer, GSDMC is considered an oncogene, as its expression is increased and supports cancer cell proliferation." (PMID 37771587, 2023). "In these studies, it was demonstrated that GSDMC played a crucial role in cancer development, especially in pyroptosis." (PMID 37359371, 2023). "We conducted a pan-cancer analysis of the expression and prognosis of GSDMC utilizing multidimensional data from The Cancer Genome Atlas (TCGA)." (PMID 36042287, 2022). "It is noteworthy that nuclear programmed death ligand 1 (nPD-L1) can upregulate GSDMC, whereas TNF-α-activated caspase-8 can cleave GSDMC, which will switch apoptosis to pyroptosis in cancer cells." (PMID 35962439, 2022). "Next, we carried out a pan-cancer survival analysis of the expression of GSDMC utilizing the TCGA database, after which the GEPIA database and KM plotter were employed for validation." (PMID 36042287, 2022). "This GSDMC/caspase-8-mediated cell death provides new and valuable insights into the pathway of cancer cell pyrolysis." (PMID 35957895, 2022). "Then we utilized the KM plotter to explore the link between the levels of GSDMC expression and patient prognosis in various pan-cancer types." (PMID 36042287, 2022).